FASN (fatty acid synthase)
Diseases named in the same sentence as FASN in open-access papers (continued):
Sharing a sentence is not in itself a finding about the gene and the disease.
breast cancer (continued). "Fatty acid synthase (FASN) is essential for the survival and maintenance of the malignant phenotype of breast cancer cells." (PMID 24866893, 2014). "FASN inhibition reduces cell proliferation and induces apoptosis in vitro and decreases the size of prostate, ovarian and breast cancer xenografts." (PMID 24964211, 2014). "Among hormone-independent and hormone-dependent cell lines, hormone-independent breast cancer cells SKBR3 expressed higher (~2.5-fold) levels of FASN compared to hormone-dependent breast cancer cells." (PMID 24778702, 2014). "As a metabolic oncogene, FASN is constitutively overexpressed and hyperactive in aggressive breast carcinoma." (PMID 24866893, 2014). "FASN is a multifunctional enzyme involved in the synthesis of palmitate from acetyl CoA/malonyl CoA and is reported to play a role in drug resistance in breast cancer cells." (PMID 23613870, 2013). "A transcriptome analysis of HER2 in breast cancer cells has revealed a molecular connection between FASN and HER2 through the PI3K/Akt pathway." (PMID 23725225, 2013). "FASN inhibitors have been shown to be effective in chemoprevention of breast cancer in HER2/neu transgenic mice and in reducing the incidence of chemically induced lung tumorigenesis." (PMID 24203995, 2013). "Overexpression of FASN, in fact, is a predictor of recurrence in stage I breast carcinoma, lung carcinoma, endometrial carcinoma patients and correlate with a worst prognosis in breast carcinoma and ovarian carcinoma patients." (PMID 24958265, 2013). "It has been described that orlistat is a potent and selective inhibitor of FASN in prostate carcinoma cells and in breast cancer cells." (PMID 23029529, 2012). "Several data supported a relationship between HER2 and FASN in breast cancer, head and neck carcinomas, HER2-overexpressed fibroblasts and other carcinomas." (PMID 22769244, 2012). "In this regard, two previous reports have observed that the protein expression of FASN in prostate and breast cancer is regulated at the post-transcriptional level." (PMID 22485149, 2012). "For instance, the Akt signaling pathway and HER-2 have been reported to play a role in upregulating FASN expression in breast cancer as well as in thyroid papillary carcinoma." (PMID 22485149, 2012). "It has been recently found that FASN is highly expressed in many types of human solid tumors, such as carcinomas of the breast, prostate, colon, ovary, thyroid, lung and stomach." (PMID 22485149, 2012). "Inhibition of FASN suppressed the growth of cancer stem-like cells in breast cancer and colon cancer, and induced apoptosis in diffuse large B-cell lymphoma and in gastric-tumor-bearing mice." (PMID 22152097, 2011). "FASN expression is up-regulated in the early steps of breast cancer and represents a therapeutic target for breast cancer metastasis and liposarcoma." (PMID 22152097, 2011). "In a xenograft model of breast carcinoma cells that are FASN+ and HER2+, we have characterised the anticancer activity and the toxicity profile of G28UCM, the lead compound of a novel family of synthetic FASN inhibitors." (PMID 22177475, 2011). "In the current study, we have characterised molecularly the in vivo anticancer activity of G28UCM in a model of FASN+/HER2+ breast carcinoma." (PMID 22177475, 2011). "In cell culture studies, α-linolenic acid (increased in the canola oil diet) has been shown to be tumoricidal to breast cancer cells and to inhibit the overexpression of fatty acid synthase." (PMID 20205934, 2010). "Since invasion is one of the key steps in the metastatic process, we further investigated the role of FASN in the invasion of breast cancer cells." (PMID 21080941, 2010). "Our data demonstrate that HRG can activate the HER2 tyrosine kinase (not the serine or threonine kinase), thus leading to interaction between HER2 and FASN and subsequently inducing the tyrosine phosphorylation of FASN in human breast cancer cells." (PMID 21080941, 2010).
breast cancer (continued). "In a direct comparison of FASN expression with Mb in a subset (n=293) of our breast cancer cohort, a highly significant correlation of both proteins was found (cc=0.297, P=0.001)." (PMID 20531416, 2010). "Our results show that lapatinib inhibits HER2-induced FASN phosphorylation and suppresses FASN activity in HER2-overexpressing breast cancer cells." (PMID 21080941, 2010). "We showed a direct correlation between the tyrosine phosphorylation and activity of FASN in breast cancer cells." (PMID 21080941, 2010). "Because of the known connection between FASN and HER2 in breast cancer cells, we focused on FASN for the subsequent experiments." (PMID 21080941, 2010). "Our current results suggest that FASN dephosphorylation plays an important role in the antitumor activity of lapatinib in HER2-positive breast cancer cells." (PMID 21080941, 2010). "It has been shown that ectopic overexpression of FASN results in drug resistance and that reducing the FASN expression increased the drug sensitivity in breast cancer cell lines." (PMID 20508725, 2010). "Using mass spectrometry, we identified FASN as one of the proteins that is dephosphorylated by lapatinib in SKBR3 breast cancer cells." (PMID 21080941, 2010). "Our data support a potential role for FASN phosphorylation as a novel therapeutic target in HER2-overexpressing breast cancer." (PMID 21080941, 2010). "Pharmacologically induced or siRNA-induced inhibition of FASN in breast cancer cells results in major changes in the synthesis of phospholipids that, in turn, impair the proper localization of HER2 to the cell membrane." (PMID 21080941, 2010). "In many types of cancer, including breast cancer, FASN overexpression robustly induces de novo lipogenesis." (PMID 21080941, 2010). "We showed that suppression of FASN by C75 or si-FASN inhibited the HRG-enhanced invasion of HER2-overexpressing breast cancer cells." (PMID 21080941, 2010). "Treating tumour cells with pharmacological inhibitors of FASN effectively suppresses growth and induces apoptosis in breast cancer cells both in vitro and in vivo." (PMID 19352381, 2009). "ERBB2-positive breast cancer cells are sensitive to inhibition of both FASN and malic enzyme 1 genes (Kourtidis A, Carkner RD, Eifert C, Brosnan MJ, Conklin DS; unpublished data)." (PMID 19298655, 2009). "It is well established that upregulation of FASN is a frequent molecular event in breast cancer." (PMID 40733158, 2025). "Mechanistically, we hypothesized that FASN serves as a key target for resveratrol-induced apoptosis in breast cancer cells." (PMID 40733158, 2025). "This dual action—on both FASN expression and catalytic function—may contribute to the broad-spectrum pro-apoptotic effects observed in various breast cancer models." (PMID 40733158, 2025). "Targeting de novo synthesis in the presence of endocrine drugs selectively impacted cell growth and did not correlate with LD reduction, suggesting endocrine resistant breast cancer cells may evade FASN inhibition through other lipid metabolic pathways." (PMID 40055794, 2025). "Thus, inhibiting lipid metabolism using drugs such as statins, the inhibitor of carnitine palmitoyltransferase I (CPT1) etomoxir and the inhibitor of fatty acid synthase (FASN) TVB-2640 is emerging as a new strategy to counteract breast cancer chemoresistance." (PMID 39863855, 2025). "High expression of FASN also significantly correlated with HER2+ status and brain metastasis, suggesting FASN could serve as a potential biomarker for distinguishing HER2-enriched breast cancer and predicting metastasis at later stage of malignancy." (PMID 41154605, 2025). "Importantly, however, only one study has directly demonstrated that FASN inhibition reduced breast cancer metastasis—specifically to brain." (PMID 40640944, 2025). "Notably, we observed that resveratrol exerts similar FASN-targeting effects across multiple breast cancer cell lines representing distinct molecular subtypes." (PMID 40733158, 2025).
breast cancer (continued). "Consequently, FASN inhibition represents a rational strategy for breast cancer treatment, especially in metabolically active subtypes such as TNBC." (PMID 40733158, 2025). "The inhibition of FASN could inhibit the growth of brain metastases in patients with breast cancer, suggesting that FASN is a potential therapeutic target for treating breast cancer metastasis." (PMID 39402211, 2025). "Moreover, trastuzumab-resistant HER2-positive breast cancer cell lines showed lower microRNAs-449 and higher Fatty Acid Synthase (FASN) expression, compared to sensitive cell lines." (PMID 40133809, 2025). "For example, FABP5 is highly expressed in colorectal and breast cancer cells, upregulating fatty acid synthase (FASN) and sterol regulatory element-binding protein (SREBP) to drive de novo fatty acid synthesis, providing raw materials for cell membrane construction." (PMID 40717587, 2025). "In breast cancer cells, hsa-miR-195 induces apoptosis by targeting genes such as Bcl-2 and FASN." (PMID 41210882, 2025). "Moreover, a recent study demonstrated that FASN inhibition by TVB-2640 slows migration and reduces invasion of MDA-MB-231 breast cancer cells and its brain metastatic variant MDA-MB-231BR." (PMID 40214422, 2025). "Also, FASN inhibition by either siRNA or exogenous inhibitor increases cisplatin-induced apoptotic cell death in MDA-MB-231 breast cancer cells." (PMID 40214422, 2025). "A high level of fatty acid synthase (FASN) is found in breast cancer." (PMID 41203126, 2025). "It is possible that downregulation of FASN by 1E5 may similarly increase ETV3/PEA3 in HER2-positive breast cancer cells." (PMID 38730603, 2024). "Meanwhile, several researchers revealed EGCG attenuated EGF-induced FASN expression at protein and mRNA levels, suppressed Akt activation, and blocked the contact of transcription factor Sp-1 with its target gene in breast cancer cells, thus exerting its anti-proliferative pharmacological effects." (PMID 38348027, 2024). "Furthermore, transient FASN knockdown in another breast cancer cell line, MDA-MB-468, consistently upregulated p65 expression." (PMID 38467328, 2024). "FASN can be used as a therapeutic target for brain metastasis of breast cancer." (PMID 39588377, 2024). "Moreover, pharmacological inhibition of FASN in HER2-positive breast cancer cells resulted in the accumulation of ETV4/PEA3, a transcriptional repressor of the HER2 gene, and reduced HER2 transcript and protein levels." (PMID 38730603, 2024). "Thus, the CircWHSC1 /miR-195-5p/FASN axis was present in breast cancer cells to influence breast cancer progression." (PMID 38408962, 2024). "Targeting FASN may therefore hold promise to inhibit tumor cell growth and enhance the vulnerability of breast cancer cells to traditional anticancer treatments." (PMID 39834807, 2024). "paniculata ethanolic crude extract as a FASN inhibitor and hence might have the potential to be further developed as a potent chemotherapeutic drug for breast cancer treatment." (PMID 38939097, 2024). "The genetic and pharmacological inhibition of FASN suppresses breast cancer growth in the brain, indicating that fatty acid synthesis could potentially serve as a therapeutic target for breast cancer brain metastases." (PMID 38921453, 2024). "Notably, FASN was reported to be the greatest in HER2-positive breast cancer and the lowest in TNBC at both the cell and tissue levels." (PMID 39791706, 2024). "FASN is under the direct transcriptional control of LXRβ in breast cancer." (PMID 38730603, 2024). "Consequently, FASN has come into focus as an appealing potential target for breast cancer treatment." (PMID 38939097, 2024). "Additionally, in various cancer cell types, including glioma, pancreatic tumors, and breast cancer, fatty acid synthase (FASN) was identified as an essential factor in CSC survival." (PMID 38370376, 2024).
breast cancer (continued). "FASN may inhibit the development and progression of breast cancer by altering the levels of specific fatty acids (LysoPC (16:0/0:0), LysoPE (16:0/0:0), or L-acetylcarnitine)." (PMID 36674685, 2023). "Correlations of FASN and clinicopathological characteristics in patients with breast cancer." (PMID 37124526, 2023). "Additionally, the results support the notion that targeted inhibition of FASN can reduce the tumor size of breast cancer patients." (PMID 37124526, 2023). "In addition, Brusselman and colleagues showed kaempferol-mediated inhibition of FASN and lipogenesis in prostate and breast cancer cells." (PMID 38001865, 2023). "Accordingly, FASN can be considered a therapeutic target in breast cancer treatment." (PMID 38017510, 2023). "The activation of FASN-driven lipogenesis phenotype may increase the aggressiveness of HER2-overexpress breast cancer." (PMID 37124526, 2023). "In other words, FASN promotes breast cancer metastasis by altering lipid metabolism." (PMID 38017510, 2023). "Moreover, BRAF inhibition (BRAFi)-resistant melanoma cells were shown to present with deregulation of the fatty acid synthase (FASN), which was proposed as a metabolic target for melanoma, prostate, and breast cancer treatment." (PMID 37495601, 2023). "Furthermore, FASN mediates the epithelial-mesenchymal transition (EMT) of breast cancer cells as its inhibition with cerulenin increases and decreases respectively the expression of E-cadherin and vimentin, and inhibits cell migration." (PMID 36934087, 2023). "It was evident that expression of FASN is commensurate with the tumor's grade and resistance to therapeutic agents such as tamoxifen (estrogen receptor antagonists), as observed in endocrine therapy in ER+ breast cancer." (PMID 38017510, 2023). "FASN overexpression was found in many types of tumor cells including breast cancer." (PMID 37124526, 2023). "Moreover, FASN has been detected in cell lysate and supernatant of breast cancer cells derived from NHW patients." (PMID 37495653, 2023). "Additionally, CYH33, in combination with C75, induces immune activation and enhances anti-tumor immunity, providing a rationale for the concurrent targeting of PI3K and FASN in breast cancer treatment." (PMID 37700339, 2023). "Thus, FASN is overexpressed in breast cancer but also in many other types of cancers: colorectal, prostate, stomach, esophageal, lung, pancreatic, ovarian, hepatic, melanoma, glioma and in primary effusion lymphoma (PEL)." (PMID 36934087, 2023). "Four studies investigated the link between FASN expression and the OS of breast cancer patients." (PMID 37124526, 2023). "Furthermore, tumour suppression via suppression of ACACA and FASN in breast cancer tissues and potential developmental abnormalities were investigated in Nfyav1-specific knockout mice." (PMID 37268670, 2023). "Higher activity of FASN was observed in breast-cancer cells." (PMID 37316878, 2023). "FASN can promote EMT in breast cancer, while inhibition of FASN can reverse the EMT process." (PMID 37056351, 2023). "It is possible that FASN may indirectly increase the aggressiveness of HER2-overexpress breast cancer by upregulation of HER2 expression." (PMID 37124526, 2023). "We speculated whether the up-regulation of palmitic acid and other fatty acids in breast cancer region was caused by the abnormal expression of ACC and FASN." (PMID 37120513, 2023). "As a result, patuletin may be considered a natural inhibitor of FASN, inducing anti-proliferative and pro-apoptotic effects in human breast cancer." (PMID 36364014, 2022). "Moreover, the consequences of increased FASN expression in breast cancer should also be considered for future directions." (PMID 36096767, 2022). "Thus, to our knowledge, this is the first study demonstrating an IGF-1 induced localization of SRSF-1 in breast cancer and its ability to regulate FASN expression." (PMID 36096767, 2022).
breast cancer (continued). "FASN is a critical enzyme of synthetizing long-chain FAs from malonyl-CoA and acetyl-coenzyme A (CoA) and has been identified at high levels in several human cancers such as prostate cancer, pancreatic cancer, breast cancer, and colorectal cancer." (PMID 35401213, 2022). "Pro-tumorigenic impact of oestradiol on FASN in breast cancer could, therefore, be significantly inhibited with DHA supplementation in combination with Akt-inhibiting agents." (PMID 35448537, 2022). "Thus, the present study identifies the IGF-1-IGF-1R-mTOR axis as an integral signaling axis in the regulation of FASN in breast cancer." (PMID 36096767, 2022). "Breast cancer cells exhibit high expression levels of FASN and activity." (PMID 35350838, 2022). "These current findings establish a potential IGF-1-mTORC1-SRPK2-FASN axis in breast cancer, which could be a potential therapeutic target for cancers that overexpress FASN and components of the IGF-1R pathway." (PMID 36096767, 2022). "FASN also induced the resistance of breast cancer cells to CDDP-induced apoptosis." (PMID 36359776, 2022). "High FASN expression is related to poor prognosis and metastasis in breast cancer." (PMID 35392075, 2022). "The formation of LDs in breast cancer is correlated with estrogen receptor and progesterone receptor, while the development of ovarian cancer is controlled by increased LD formation, which is mediated by FASN expression." (PMID 35790992, 2022). "Likewise, FASN, a rate-limiting enzyme in the saturated long-chain fatty acid synthesis pathway, is an interesting target for breast cancer therapy." (PMID 34986886, 2022). "In breast cancer cell lines, SUMOylation prevents FASN degradation by the proteasome, and the reduction in SUMOylation caused by SUMO2 silencing reduces the stability of FASN and inhibits the development of tumor cells." (PMID 35392171, 2022). "Moreover, the twenty-three types of cancer, include almost all the high-incidence and high-mortality cancer types, except breast cancer, which further illustrated the carcinogenesis of FASN in the tumor progression." (PMID 36555243, 2022). "The divergence in FASN expression between the different types of metastatic tumours could be one of the clinical criteria in deciding whether to treat breast-cancer-metastasised patients using FASN inhibitors based on the anatomical location of the metastasis." (PMID 35448537, 2022). "Thus, FASN warrants consideration as a therapeutically targetable driver of tamoxifen resistance in ER/HER2-positive breast cancer." (PMID 33800852, 2021). "Based on our analysis, FASN had a higher expression at the protein level in breast cancer." (PMID 34879004, 2021). "Pharmacological blockade with structurally and mechanistically unrelated FASN inhibitors fully impeded the strong stimulatory activity of tamoxifen on the soft-agar colony forming capacity—an in vitro metric of tumorigenicity—of ER+/HER2+ breast cancer cells." (PMID 33800852, 2021). "Furthermore, activation of LXRs decreases the expression of lipogenic genes (e.g., SREBP1c, SCD1, and FASN) in breast cancer cells." (PMID 34775964, 2021). "Our results suggest that FASN expression might correlate with the sensitivity of ER+/HER2+ luminal B-like breast cancer cells to adjuvant endocrine therapy." (PMID 33800852, 2021). "C75, an FASN inhibitor has more stable chemical properties than cerulenin, and also shows a strong inhibitory effect on a variety of human cancer cell lines, including breast cancer, prostate cancer, mesothelioma, and ovarian cancer." (PMID 34766135, 2021). "Furthermore, epithelial breast cancer cells with high expression of E-cadherin showed high expression of FASN, while mesenchymal cells with high expression of vimentin showed high expression of carnitine palmitoyltransferase-1 and therefore of β-oxidation." (PMID 33808259, 2021). "Moreover, FASN has been detected inside autophagosomes, for instance in yeast and in the breast cancer cell line MCF7." (PMID 33742137, 2021).